ENSG00000287694 (novel protein)
Gene: Protein-coding gene on chromosome 16 (76,277,288 to 76,819,624, forward strand). Ensembl gene ENSG00000287694.
Genetic constraint (gnomAD): Missense variants: 1,553 observed, 1,299.9 expected, observed/expected ratio (o/e) 1.19, 90% interval 1.14 to 1.25. Synonymous variants: 602 observed, 477.27 expected, observed/expected ratio (o/e) 1.26, 90% interval 1.18 to 1.35.